HDAC4 (histone deacetylase 4)
Diseases named in the same sentence as HDAC4 in open-access papers (continued):
Sharing a sentence is not in itself a finding about the gene and the disease.
cancer (continued). "1H-HRMAS technology revealedmetabolomically distinct groups according to the expression of HDAC1, HDAC4 andSIRT1, suggesting that these genes may play an important role in regulating braintumorigenesis and cancer progression." (PMID 25791281, 2015). "Meanwhile, several previous studies have demonstrated various roles for HDAC4 in cancer cells." (PMID 25557107, 2015). "Our analysis indicates two distinct and mutually exclusive types of cancers, one associated with a gene expression pattern of EZH2 activation and tyrosine kinase signaling and the other with HDAC4 activation with increased cytokine signaling and immune cell infiltration." (PMID 24079712, 2013). "Epigenetic alterations, such as DNA methylation or histone modification, in cancer often mediate the deregulation of tumour suppressors or oncogenes, and HDAC4 expression potentiated by miR-22 downregulation may further aggravate the epigenetic changes in HCC." (PMID 20842113, 2010). "Therefore, HDAC4 may be a useful biomarker for diagnosis and prognosis of cancer patients or a potential target for anti-cancer therapy." (PMID 27295551, 2016). "Thus, we speculated autophagy occurred may protect SGC-7901 cancer cells apoptosis induced by HDAC4 knockdown." (PMID 24896240, 2014). "Hence, exposure of cancer and endothelial cells to 0.5-1μM concentrations of tasquinimod will produce intracellular levels of 2 to 3 μM or more than twenty-fold higher than needed to bind and thus also inhibit HDAC4 and S100A9." (PMID 25193858, 2014). "Therefore, we might speculate that the mechanism through which SAHA leads to a reduction in HDAC4 is through RANBP2-mediated proteasome degradation as determined for cancer cell lines." (PMID 22140466, 2011). "Very little is known about the interaction between HDAC4 and YAP and how they work together to regulate cancer promotion." (PMID 41281751, 2025). "We found that a 4-hour treatment with the pan-HDACs or HDAC4 inhibitor in MIA PaCa-2 and BxPC3 cancer cells decreased the protein levels of MybL1." (PMID 41281751, 2025). "HDAC4 has been identified as a key regulator of EMT, and its overexpression enhances tumor invasiveness in various cancers." (PMID 40332124, 2025). "The precise molecular mechanisms underlying HDAC4's role in cancer remain incompletely understood, but it may involve interactions with the corepressor complex NCOR1/NCOR2/HDAC3 and influence the transcription landscape of cancer cells through epigenomic reprogramming." (PMID 38911380, 2024). "Specifically, HDAC4, HDAC5, KAT2B, NCOA1, SIRT1, and SIRT4 had lower expression in tumor tissues across 14, 12, 18, 17, 16, and 12 cancer types, respectively." (PMID 39906742, 2024). "WIPI2, COL4A2, HDAC4, CUGBP2, PTPRN2 and RUNX2 are Top 6 differential methylation genes, and all of them were reported to take part in regulation of cancers." (PMID 36817452, 2023). "Therefore, it is plausible that truncated versions of HDAC4 might have a biological role in cancer." (PMID 36762207, 2023). "Supporting the putative oncogenic activity of HDAC4, mouse models with deregulated class IIa HDACs-HDAC7 or HDAC9-have been reported to develop cancer." (PMID 36762207, 2023). "The ability of HDAC4 to repress the expression of tumor suppressor genes, such as CDKN1A, further supports a positive role of the deacetylase in cancer cells growth." (PMID 36762207, 2023). "Our results showed that HDAC4 promotes the growth and migration of NSCLC cells, which is consistent with the findings in other cancers." (PMID 35864951, 2022). "Our results above showed HDAC4 activated GAC, an oncogene involved in tumorigenesis and progression in various human cancers." (PMID 35864951, 2022). "LMK235, an inhibitor of HDAC4 and HDAC5, has been investigated for its antitumor effect on other cancers." (PMID 36139696, 2022).
cancer (continued). "miR-1 targets several cancer-related molecules, such as Slug, PI3KCA, FoxP1, Pim-1, HDAC4, CCDN2, and CXCR4, indicating that miR-1-3p regulates the expression of several oncogenic pathways." (PMID 35804872, 2022). "HDAC4 repressed the expression of CDKN1A in human cancer cells, and silencing of HDAC4 induced CDKN1A expression and inhibited cancer cell growth in vitro and in an in vivo human GBM model." (PMID 36139696, 2022). "HDAC4 has been shown to be involved in immune regulation, while HDAC10 plays roles in DNA repair, autophagy and anti-cancer responses." (PMID 33898439, 2021). "Other scholars investigated the relationship between HDAC4 regulation of HIF-1, VEGF and angiogenesis in cancer cell line." (PMID 32354322, 2020). "Among the recurrent genomic events, those in BRD9, EP300, ATAD2, HDAC4, PRBM1, BRD4, and BRD1 were observed in the highest numbers of cancer types (nine, eight, eight, eight, seven, seven, and seven, respectively)." (PMID 30760718, 2019). "The HDAC4, HDAC10, and SIRT3 copy numbers were recurrently lost in eight, six, and six cancer types, respectively." (PMID 30760718, 2019). "Studies have shown that histone deacetylase 4 (HDAC4) and proliferating cell nuclear antigen (PCNA) are highly expressed in cancers." (PMID 31552187, 2019). "Our results indicate that certain HDAC genes (e.g., HDAC4 and HDAC10) focally lose copy numbers in selected cancer types." (PMID 30760718, 2019). "Target genes of miR-22 so far reported include HDAC4, CDK6, SIRT1, SP1, HIF-1α and PTEN, which are involved in cancer progression." (PMID 30379969, 2018). "LMK-235, a novel HDAC class IIA HDACi specifically inhibiting HDAC5 (IC50 = 4.22 nM) and HDAC4 (IC50 = 11.9 nM), was found to be cytotoxic in several human cancer cell lines." (PMID 30321986, 2018). "Histone deacetylase 4 (HDAC4) and Cyclin-dependent kinase inhibitor 1A (CDKN1A) are two critical proteins in cancer, and both are directly targeted and regulated by miR-22." (PMID 28045918, 2017). "In contrast, LMK-235, a novel class IIa HDACi with a preference for HDAC4 and HDAC5, displayed potent cytotoxic effects in human cancer cell lines." (PMID 27177225, 2016). "For example, overexpression of HDAC1, HDAC2, HDAC4, HDAC6, and HDAC7 has been observed in various cancers." (PMID 27902771, 2016). "Tasquinimod, an orally active quinoline-3-carboxamide, binds with high affinity to HDAC4 and S100A9 in cancer and infiltrating host cells within compromised tumor microenvironment inhibiting adaptive survival pathways needed for an angiogenic response." (PMID 25193858, 2014). "Such tumor angiogenesis requires HDAC4 and S100A9 dependent signaling in the cancer cells themselves as well as in the infiltrating host cells." (PMID 25193858, 2014). "In addition, histone deacetylase 4 (HDAC4), known to have critical roles in cancer development, is proved to be targeted and regulated by miR-22, indicating that downregulation of miR-22 may involve in HCC carcinogenesis and progression through potentiation of HDAC4 expression." (PMID 20842113, 2010). "Importantly, we found that both the pan-HDAC inhibitor Saha and the HDAC4 specific inhibitor Lmk-235 significantly decreased the mRNA level of the transcription factor MybL1 in MIA PaCa-2 and PANC-1 cancer cells." (PMID 41281751, 2025). "Our studies demonstrate a hitherto unknown interaction between HDAC4 and YAP responsible for regulating metastasis in cancers, including PDAC." (PMID 41281751, 2025). "The coordinated inhibition of HDAC6, HDAC3, and HDAC4 by BKS-112 may synergistically contribute to its potent anticancer effects, as these isoforms play distinct but complementary roles in cancer cell survival and progression." (PMID 41300448, 2025). "As frequently observed for other epigenetic regulators, the contribution of HDAC4 to cancer seems to be context-dependent and therefore not easy to categorize." (PMID 36762207, 2023). "HDAC4 induced EMT and cancer stem cell-like properties in cancer cells." (PMID 35682560, 2022).
cancer (continued). "In particular, CDK6 was chosen for the function “pathway in cancer”, ADAM12 for the function “signaling by EGFR”, HDAC4 was selected for the function “regulation of cell differentiation”, and finally Bcl2 for the function “negative regulation of apoptotic processing”." (PMID 36498866, 2022). "Clarifying the mechanisms that enact HDAC4 and HDAC5 localization induced by μsPEF exposure of mammalian cells has significant translational implications due to the pervasive roles of class IIa HDAC’s in cancer." (PMID 36466344, 2022). "Together, our results demonstrate that inhibition of HDAC4 activity impairs the proliferation of cells that overexpress MELK more than cells that do not overexpress MELK, thus revealing a potential targetable vulnerability of cancers that overexpress MELK." (PMID 34550356, 2021). "Additionally, there are very significant differences between the two groups in methylation of specific genes known to be important in UM and in cancer progression in general, including PTEN, NFIA, IL12RB2, RASSF1, and HDAC4." (PMID 33092094, 2020). "Relative PAM, STC1, and HDAC4 expression were down-regulated, whereas CASP6, CHST6, SLC16A3, TPI1, KDELR3, VCAN, and CLDN9 were highly expressed in carcinoma tissues compared to the para-carcinoma tissues." (PMID 33424916, 2020). "Class I histone deacetylases (HDACs) generally promote cell proliferation and tumorigenesis, whereas class IIA HDACs like HDAC4 and HDAC5 may promote or impede cancer development in a tissue-dependent manner." (PMID 31052182, 2019). "HDAC4, which is a class II HDAC Zn2+ dependent enzyme has also been shown to be an important target for other neurological disorders and other cancer types as well." (PMID 31905609, 2019). "It has been shown that the administration of SAHA to wild type and R6/2 mice decreased HDAC2 and HDAC4 at the protein but not RNA levels in different brain regions in vivo, supporting previous observations from cancer cell lines." (PMID 25759639, 2015). "Additional studies document that when tasquinimod binds to the open conformation of HDAC4, it prevents binding of N-CoR/HDAC3 thus preventing client protein deacetylation in both hypoxic cancer cells and their endothelial support cells needed for survival signaling and angiogenesis." (PMID 25193858, 2014). "HDAC4 regulates hypoxia-inducible factor 1 α (HIF1 α) and cancer cell response to hypoxia." (PMID 23819581, 2013). "In cancers characterised by high levels of NRF2, HDAC4 localises in the nucleus and represses the expression of these miRNA, resulting in increased nucleic acid and lipid synthesis, thereby providing a mechanism by which NRF2 can increase cellular proliferation in these cancer cells." (PMID 24029073, 2013). "These analyses led to the novel conclusion that activation of HDAC4 and the histone methylase EZH2 are mutually exclusive and represent two distinct biologic fates in cancer cells, one related to growth factor signaling and the other related to inflammatory signaling." (PMID 24079712, 2013). "Our demonstration that the administration of SAHA to wild type and R6/2 mice decreases the levels of HDAC2 and HDAC4 at the protein and not RNA levels extends previous observations in cancer cell lines to the in vivo situation." (PMID 22140466, 2011). "Furthermore, histone deacetylase 4 (HDAC4), known to have critical roles in cancer development, was proved to be directly targeted and regulated by miR-22." (PMID 20842113, 2010). "Interestingly, HDAC10 alone was down-regulated in HCC827 cells, but there was no change observed in HDAC2 or HDAC4 in either cancer cell line." (PMID 40941018, 2025). "Two other HDAC4 inhibitors, mocetinostat dihydrobromide and a class IIa HDAC inhibitor, both developed by MethylGene Inc., are undergoing extensive clinical trials for the treatment of multiple cancers including advanced solid tumor and metastatic non-small-cell lung cancer." (PMID 35814270, 2022).
cancer (continued). "Although both vorinostat and DMC-HA are inert to HDAC4 and HDAC5, it has been reported that class IIa (including HDACs 4, 5, 7, and 9) enzymes are inefficient on histone substrates; class I HDACs, especially HDACs 1–3, and HDAC 6 (class IIb) are considered key targets for cancer treatment." (PMID 34804949, 2021). "Thereafter, PRL-3 itself again may be considered as a potential therapeutic target in diseases due to epigenetic abnormal regulation, including various types of cancer, rather than HDAC4 that would raise generally intrinsic side effect if targeted." (PMID 31887658, 2020). "We further confirm our finding by ELISA-based activity studies of HDAC4, Akt and S6K1 which further confirm that mTORC2 and SIK3 are sequentially activated by IL-17 and high salt, respectively, to potentially induce a synergistic inflammatory and cell proliferation effect in cancer cells." (PMID 28658303, 2017). "Together with the notion that a high level of HDAC4, HDAC5 and HDAC6 expression has an implication in cancer development, the up-regulation of HDAC4, HDAC5 and HDAC6 of fPMSCs showed in this study may imply a potential risk for malignant transformation for this type of cells." (PMID 25671548, 2015). "However, there is no selective HDAC4 inhibitor to date that necessitates the use of SAHA or TSA to target HDAC4 for both neurodegenerative disease and cancer." (PMID 31067680, 2019).
tumor (125 papers, 2006 to 2026). "TMP195 is a selective class IIa HDAC (HDAC4, -5, -7, and -9) inhibitor that has been reported to reprogram tumor-associated macrophages into tumoricidal cells and reduce tumor burden in breast cancer." (PMID 36263186, 2022). "Anisomycin restored the tumour suppression caused by HDAC4 knockdown, suggesting that HDAC4 acts as an upstream effector of p38." (PMID 35637410, 2022). "Delayed tumor growth in vivo by the combinational treatment of RT and HDACi/HDAC4-KD was shown with the associated NKG2D ligand expressions." (PMID 36185276, 2022). "For example, HDAC4 expression not only is significantly associated with tumor size in malignant thyroid lesions but also promotes tumor growth through suppressing p21 expression in colon cancer, glioblastoma, ovarian cancer, and gastric cancer cells." (PMID 27295551, 2016). "HDAC4 overexpression is associated with higher tumor grade, advanced clinical stage and poor survival." (PMID 27295551, 2016). "Mutations and dysregulated expression of HDAC4 have been observed in various tumor types." (PMID 38911380, 2024). "More importantly, we identified that HDAC4 positively regulates TET2 expression, and HDAC4 knockout significantly enhanced colony forming capacity of murine MDS cells, indicating that HDAC4 serves as a tumor-suppressor in the context of high-risk MDS or normal karyotype AML." (PMID 32726753, 2020). "Notably, elevated expression of HDAC4 is known to promote tumor formations, whereas its chemical inhibitors and siRNA-mediated knockdown of HDAC4 are associated with regressions of cell growth." (PMID 24755370, 2014). "Therefore, the anti-tumor activity of HDAC4/5 inhibitor may be partly caused by increasing SerRS acetylation and nuclear localization." (PMID 34400610, 2021). "Given the importance of genes that regulate tumor immune responses, the aim of our study was to determine the role of one such gene named histone deacetylase 4 (HDAC4) with the objective of evaluating its impact in the tumor microenvironment (TME)." (PMID 40361444, 2025). "Further, these expression scores revealed that patients with HDAC4 deletion tend to have higher tumor proliferation compared to WT." (PMID 40693457, 2025). "We further assessed the mRNA expression of all Class I HDACs (HDAC1, 2, 3 and 8), as well as previously reported HDAC4 (a Class IIa HDAC) in tumor organoids using qRT-PCR." (PMID 39567475, 2024). "WB of the harvested tumor tissues showed that circCGNL1 overexpression significantly inhibited HDAC4 phosphorylation and RUNX2 expression but promoted GAMT expression." (PMID 38297362, 2024). "For example, the expression of HDAC2/3/7/10 and SIRT2/3/6/7 associates with tumor size in BRCA, the level of HDAC4/5/8/10/11 and SIRT1/5/7 associates with tumor size in KIRC, and the upregulation of HDAC2/4/6/7 and SIRT1/2/6 associates with tumor size in LUAD." (PMID 39063083, 2024). "In order to evaluate the clinical implications of HDAC4, we used immunohistochemistry to assess HDAC4 expression in 165 primary tumor tissues from patients with CRC (stage III) and analyzed the relationship between HDAC4 expression and disease-free survival." (PMID 38473392, 2024). "In conclusion, class IIa HDACi—firstly—reduce tumor growth of HNSCC with high HDAC4 expression and—secondly—act synergistically in combination with proteasome inhibitors in platinum-resistant HNSCC." (PMID 36982651, 2023). "The same result was obtained in the in vivo CAM model: HDAC4 overexpressing cells showed significantly increased tumor volume compared to vector control cells and increased, but not significantly different, tumor weight." (PMID 36982651, 2023).